PROX1 (prospero homeobox 1)
Diseases named in the same sentence as PROX1 in open-access papers (continued):
Sharing a sentence is not in itself a finding about the gene and the disease.
cancer (continued). "There is evidence that PROX1, besides lymph-/angio-genesis, directly interferes with many intracellular signaling pathways, responsible for proliferation and epithelial-mesenchymal transition (EMT) of cancer cells, a process that clearly defines cancer behavior and metastatic potential." (PMID 35885529, 2022). "Interestingly, a similar opposing pattern of PROX1:FGF2 expression was observed in all analyzed cancer cell lines, but not cells derived from normal thyroid." (PMID 31717665, 2019). "This supports the prominent role played by MMP14 in cancer metastasis indicating that a low or absent PROX1 expression may be required for MMP14 to be highly expressed." (PMID 31560170, 2019). "Moreover, by manipulating PROX1 expression we could regulate MMP14 expression in an in vivo mouse model and change the invasive properties of cancer and blood endothelial cells in vitro." (PMID 29934628, 2018). "Of the genes that were altered in all cancer subtypes, the expression of five matched all datasets (HOXC8, HOXC11, HOXD8, PROX1, SIX2), although the overlap was found when considering the expression in the majority of the subtypes as HOXC11 and PROX1 were downregulated in TN CSC." (PMID 28202042, 2017). "However, the detailed role and function of Prox1 and FOXC2 in cancer remains controversial." (PMID 24647631, 2014). "Consequently, PROX1 and MTA1 are regarded as useful biomarkers for the diagnosis, prognosis, and treatment of malignancies in humans; nevertheless, additional research is required to thoroughly evaluate their function in cancer therapy and their potential clinical application." (PMID 40660330, 2025). "However, the mutual regulation of PROX1 and FGF2 was never investigated in human cancer." (PMID 31717665, 2019).
infection (15 papers, 2009 to 2025). The state of being infected such as from the introduction of a foreign agent such as serum, vaccine, antigenic substance or organism. "Infection with lentiviruses expressing Prox1-targeting siRNA precursors si258 (lenti-si258) or si1646 (lenti-si1646) nearly obliterated endogenous Prox1 expression (top, lanes 1–3), and caused a marked increase in CYP7A1 mRNA level (bottom, bars 1–3)." (PMID 23626788, 2013). "Infection of Lyve-1-Cre and Prox1-CreERT2 mice revealed that amongst EC subsets, infection of lymphatic ECs was sufficient." (PMID 36689486, 2023). "The results of microarray analysis and qRT-PCR show that rSS1GFP infection resulted in the relatively high expression level of PROX1." (PMID 30894203, 2019). "This discovery stems from our previous observation that KSHV-infection of LECs leads to a decrease in PROX1 expression with a concomitant increase in MMP14 expression and MMP14-dependent invasiveness." (PMID 29934628, 2018). "Hepatic triglycerides (TG) were significantly elevated following 3 weeks of PROX1 knockdown, with a more striking difference in TG levels observed at 6 weeks post infection." (PMID 28916805, 2017). "By 14 and 24 days post-infection, Pax6 lentivirus-infected H1 hES cells exhibited expression of γA-crystallin, Prox1, and Tdrd7, similar to expression of the homologous mouse proteins in G4 and Pax6-GFP mES cells." (PMID 25517354, 2014). "Infection of HepG2 cells with recombinant lentiviruses expressing Prox1-targeting siRNA precursors lenti-si258 or lenti-si1646 effectively knocked down endogenous Prox1 expression, without markedly affecting LSD1 or HDAC2 expression." (PMID 23626788, 2013). "On the other hand, infection by lenti-Prox1m resulted in overexpression of Prox1 (top, lane 4) and decrease in CYP7A1 mRNA level (bottom, bar 4)." (PMID 23626788, 2013). "Our study revealed that ∼78% of the cells (n = 390) was double negative for PROX1 and LANA, and ∼18% double positive, strongly correlating PROX1 upregulation with de novo KSHV-infection." (PMID 20730087, 2010). "Throughout the remaining course of infection, PROX1 levels roughly correlated with HCV levels in the SC and TC chimpanzees, while in the PS chimpanzee the PROX1 levels remained lower than the HCV levels." (PMID 19149867, 2009). "Contrary to this, PROX1 expression was observed to rise early post-infection in the SC and TC chimpanzees." (PMID 19149867, 2009). "KSHV-infection dramatically increased H3K4me3 and decreased H3K27me3 in the PROX1 promoter." (PMID 34492084, 2021). "We examined the conditioned medium of KSHV-infected PDLSCs for its effect on PROX1 expression and found that the treatment of PDLSCs with the conditioned medium dramatically upregulated PROX1 expression in PDLSCs, especially 48 hours post-infection (48 hpi)." (PMID 34492084, 2021). "Interestingly, we and others have demonstrated that infection of LECs with KSHV reduces PROX1 expression." (PMID 29934628, 2018). "We and others have previously reported that KSHV-infection reprograms the host cell identity by triggering a drift from their original phenotypes and that PROX1, whose expression is deregulated by KSHV, plays a key role in this pathological host cell fate reprogramming." (PMID 22719258, 2012). "Expression of PROX1 in the HCV-infected chimpanzees early post-infection decreased slightly within the first six days for the SC chimpanzee, increased within the first eight days in the TC chimpanzee, and decreased within the first eight days in the PS chimpanzee." (PMID 19149867, 2009). "In our previous study, we found that KSHV-infection of oral MSCs can up-regulate PROX1 and, as a consequence, promote endothelial-lineage differentiation or MEndT, while KSHV-infection of terminally differentiated LECs down-regulates PROX1." (PMID 34492084, 2021).
infection (continued). "The result showed that some mesenchymal markers, such as COL1A1, α-SAM, and TAGLN, faded and endothelial markers PROX1 and PDPN increased starting at the fourth day post-infection." (PMID 34936683, 2021). "Western blot analyses further confirmed that the steady-state level of PROX1 protein was increased in BECs and HUVECs by KSHV infection, but significantly decreased in LECs upon KSHV-infection." (PMID 22719258, 2012). "We next set out to investigate how KSHV-infection resulted in downregulation of PROX1 in LECs, despite the fact that KSHV upregulates PROX1 in BECs and HUVECs." (PMID 22719258, 2012). "For the in vitro study, we infected cultured human dermal BECs with KSHV for 7 days and performed immunofluorescent studies for PROX1 and LANA/ORF73, a KSHV viral protein that marks a latent KSHV-infection." (PMID 20730087, 2010). "We collected tdT+ CD45− cells from the lungs of Prox1-CreERT2; R26RtdT mice at 10 dpi or without infection." (PMID 38529320, 2024). "Therefore, the reciprocal regulation between PROX1 and HEY1 adds another layer of complexity to the opposing regulatory circuits of PROX1 expression by IL3Rα and NOTCH upon KSHV-infection." (PMID 22719258, 2012). "We hypothesize that KSHV-infection results in simultaneous activation of the IL3Rα and NOTCH pathways and delivers both positive and negative regulatory signals, respectively, to the PROX1 gene in both blood and lymphatic-lineage endothelial cells." (PMID 22719258, 2012). "In contrast, infection with AAV2-Control antibody (AAV2-Ctrl Ab), expressing an scFv with no affinity to Prox1, had no such effect." (PMID 40133314, 2025). "Consistent with the published results, infection of HUVECs with KSHV led to a significant increase in the expression of XLKD1/LYVE1, VEGFR-3 and PROX-1, while treatment of HUVECs-K13-ERTAM with 4OHT failed to do so." (PMID 19660139, 2009).
adenocarcinoma (4 papers, 2021 to 2025). A common cancer characterized by the presence of malignant glandular cells. "On the other hand, adenocarcinomas, especially those with an alveolar growth pattern, were more likely to exhibit higher levels of PROX1." (PMID 40843762, 2025). "Specifically, 87.5% of adenocarcinomas in the moderate-PROX1-expression group (26–50%) exhibited mucus production (14 out of 16), compared to only 25%, 30%, and 33.3% in the low (>0–25%), high (51–75%), and very high (76–100%) groups, respectively (p = 0.002)." (PMID 40843762, 2025). "The highest proportion of mucus-producing adenocarcinomas was seen in the group with intermediate PROX1 expression (26–50%)." (PMID 40843762, 2025). "Moreover, 46.8% of the adenocarcinomas were mucus-productive, while the vast majority of these mucus-productive tumors showed additional PROX1 expression." (PMID 40843762, 2025). "Additionally, alveolar-pattern adenocarcinomas exhibited intermediate PROX1 expression (26–50%) (p = 0.010)." (PMID 40843762, 2025). "However, within subgroups comprising adenocarcinomas harboring an elevated basal level of PROX1, significant enrichment of tumors with an alveolar pattern was found in the intermediate-expression group (26–50%; p = 0.010)." (PMID 40843762, 2025). "We performed IHC to measure the expression of PROX1 along with NCAM1, AR, and the AR target, PSA, using tissue sections from samples collected at multiple time points (i.e., pre-castration adenocarcinoma [LTL331], 12 weeks post-castration, and relapsed NEPC [LTL331R])." (PMID 40454483, 2025). "Taken together, these results suggest that PROX1 upregulation is an early molecular event in castration-induced lineage plasticity prior to NEPC differentiation and may serve as a critical mediator of progression from adenocarcinoma to NEPC." (PMID 40454483, 2025).
metabolic disease (4 papers, 2020 to 2024). A congenital disorder (due to inherited enzyme abnormality) or acquired (due to failure of a metabolically important organ) disorder resulting from an abnormal metabolic process. "Single nucleotide polymorphism (SNP) in the prospero homeobox 1 (PROX1) gene is a strong genetic susceptibility factor for this metabolic disorder and impaired β-cell function." (PMID 34209638, 2021).
retinopathy (2 papers, 2022 to 2024). "These analyses showed effects of retinopathy-associated genotypes on increased gene expression for PCSK9 (rs2479409) in skin fibroblasts, for CYP2C19*2 (rs4244285) in skin fibroblasts, liver, and stomach, and for PROX1 (rs340874) in the brain (Consortium, 2015)." (PMID 35600617, 2022).
hematological cancer (1 paper, 2016). "Aberrant DNA methylation of PROX1 causing gene silencing has also been reported in hematological cancer." (PMID 27626492, 2016).
psychiatric disorder (1 paper, 2024). A disorder characterized by behavioral and/or psychological abnormalities, often accompanied by physical symptoms. "Therefore, with respect to Prox1 and beyond, examining the role of Zmiz1 in hippocampal neurogenesis and subsequent neural identity specification, connectivity, and pathological association with neurological and psychiatric disorders may provide new insights into this important topic." (PMID 38718095, 2024).
PROX1 also shares sentences with these, for which no sentence is quoted: lymphangiectasia (3 papers); metabolic syndrome (2); oligodendroglioma (2); Adult onset (1); Alzheimer disease (1); amyloid (1); anaplastic astrocytoma (1); anaplastic cancer (1); anaplastic gliomas (1); aortic stenosis (1); Ascites (1); brain arteriovenous malformations (1); cardiomyopathy (1); cataract (1); CNS tumors (1); colorectal adenocarcinoma (1); COVID-19 (1); diabetic retinopathy (1); diffuse large B-cell lymphoma (1); dilated cardiomyopathy (1); endothelial dysfunction (1); epilepsy (1); fibrosarcoma (1); gastric adenocarcinoma (1); Granuloma (1); head and neck squamous cell carcinoma (1); helminth infection (1); Hyperglycemia (1); Impaired glucose tolerance (1); Insulin resistance (1).
A further 19 diseases each share a sentence with PROX1 in 1 paper.